Y_RNA (Y RNA )
Gene: Miscellaneous RNA gene on chromosome 15 (100,638,363 to 100,638,457, forward strand). Ensembl gene ENSG00000212306.
Homologues: Orthologues: chimpanzee Y_RNA (97% identical), macaque Y_RNA (89% identical). Paralogues in human: Y_RNA (84% identical), Y_RNA (83% identical), RNY1 (82% identical), Y_RNA (82% identical), Y_RNA (81% identical), RNY1P11 (80% identical), Y_RNA (80% identical), RNY1P7 (79% identical), Y_RNA (79% identical), RNY1P8 (78% identical), Y_RNA (78% identical), RNY1P15 (77% identical), and 92 more.